MIB1 (MIB E3 ubiquitin protein ligase 1)
Description:
E3 ubiquitin-protein ligase that mediates ubiquitination of Delta receptors, which act as ligands of Notch proteins. Positively regulates the Delta-mediated Notch signaling by ubiquitinating the intracellular domain of Delta, leading to endocytosis of Delta receptors. Probably mediates ubiquitination and subsequent proteasomal degradation of DAPK1, thereby antagonizing anti-apoptotic effects of DAPK1 to promote TNF-induced apoptosis (By similarity). Involved in ubiquitination of centriolar satellite CEP131, CEP290 and PCM1 proteins and hence inhibits primary cilium formation in proliferating cells. Mediates 'Lys-63'-linked polyubiquitination of TBK1, which probably participates in kinase activation. (Microbial infection) During adenovirus infection, mediates ubiquitination of Core-capsid bridging protein. This allows viral genome delivery into nucleus for infection.
Synonyms: DIP-1; DIP1; KIAA1323; ZZANK2; MIB; ZZZ6; LVNC7
Tractability: Antibody: UniProt places it where antibodies can reach, with medium confidence; its Gene Ontology location is reachable by antibodies, with medium confidence. PROTAC: UniProt records ubiquitination sites on it; ubiquitination databases record sites on it; its protein half-life has been measured.
Gene: Protein-coding gene on chromosome 18 (21,704,957 to 21,870,953, forward strand). Ensembl gene ENSG00000101752.
Subcellular location: Cytoplasm; Cytoplasm, cytoskeleton, microtubule organizing center, centrosome, centriolar satellite; Cell membrane
Subcellular location (Human Protein Atlas): Microtubules; Primary cilium; Basal body; Centriolar satellite; Cytokinetic bridge; Mitotic spindle
Pathways (Reactome):
Disease: Constitutive Signaling by NOTCH1 HD Domain Mutants; Constitutive Signaling by NOTCH1 HD+PEST Domain Mutants; Constitutive Signaling by NOTCH1 PEST Domain Mutants
Signal Transduction: Activated NOTCH1 Transmits Signal to the Nucleus; NOTCH2 Activation and Transmission of Signal to the Nucleus; NOTCH3 Activation and Transmission of Signal to the Nucleus
Gene Ontology:
Molecular function: protein binding; ubiquitin protein ligase activity; ubiquitin-protein transferase activity; metal ion binding; zinc ion binding
Biological process: ubiquitin-dependent protein catabolic process; endocytosis; Notch signaling pathway; protein ubiquitination
Cellular component: centriolar satellite; centrosome; cytoplasm; cytosol; cytoplasmic vesicle; glutamatergic synapse; plasma membrane; postsynaptic density
Genetic constraint (gnomAD): Loss-of-function variants: 173 observed, 79.92 expected, observed/expected ratio (o/e) 2.16. Missense variants: 659 observed, 898.11 expected, observed/expected ratio (o/e) 0.73, 90% interval 0.69 to 0.78. Synonymous variants: 324 observed, 312.39 expected, observed/expected ratio (o/e) 1.04, 90% interval 0.95 to 1.14.
Gene-disease validity (ClinGen):
ClinGen rates the evidence that MIB1 causes each of these diseases.
dilated cardiomyopathy (autosomal dominant): Limited. Cardiomyopathy which is characterized by dilation and contractile dysfunction of the left and right ventricles.
Homologues: Orthologues: macaque MIB1 (99% identical), dog MIB1 (99% identical), pig MIB1 (99% identical), rabbit MIB1 (99% identical), mouse Mib1 (99% identical), rat Mib1 (99% identical), chimpanzee MIB1 (98% identical), tropical clawed frog mib1 (96% identical), zebrafish mib1 (94% identical), guinea pig MIB1 (92% identical), Drosophila melanogaster mib1 (70% identical). Paralogues in human: MIB2 (38% identical).
Diseases named in the same sentence as MIB1 in open-access papers:
MIB1 is named in the same sentence as 180 diseases in open-access papers, as found by Europe PMC text mining. Sharing a sentence is not in itself a finding about the gene and the disease. The quoted sentences say what the papers report.
meningioma (47 papers, 2007 to 2026). A generally slow growing tumor attached to the dura mater. "The present study investigated the role of the Simpson grade system, MIB-1 immunohistochemical marker, meningioma location and grade in the risk of recurrence." (PMID 39790708, 2025). "The role of MIB-1 as a key factor associated with meningioma recurrence is limited, which indicates that the risk of tumor recurrence is low." (PMID 39790708, 2025). "In this cohort, the role of MIB-1 as an important factor associated with meningioma recurrence is limited." (PMID 39790708, 2025). "As the promising markers to predict OS of meningioma patients, Ki-67/MIB-1 (HR = 1.03, 95%CI 1.02 to 1.05) was identified to associate with poor prognosis of the patients." (PMID 38758750, 2024). "Previous studies have demonstrated an association between shape and PFS in meningiomas, but this is the first report linking increased MIB-1 labeling index to postoperative cranial nerve functioning." (PMID 37370707, 2023). "MIB‐1 LI has been extensively used in studies to determine the prognosis of several types of various tumors in central nervous system, including meningiomas, and an elevated MIB‐1 LI has been associated with an increased recurrence rate." (PMID 37644780, 2023). "MIB-1 labeling index seems to be strongly correlated with an increased risk of tumor progression in sporadic spinal meningioma." (PMID 36091152, 2022). "Several investigations have demonstrated that an increased MIB-1/Ki-67 labeling index is an independent risk factor for meningioma progression." (PMID 36077817, 2022). "A high MIB-1 labeling index is strongly associated with shorter progression-free survival in meningioma and positively correlates with the meningioma grade." (PMID 34298854, 2021). "Recently we have found that the FORGE score can estimate high MIB-1 labeling indices which are strongly associated with tumor progression in meningioma." (PMID 34829359, 2021). "An established factor that is associated with a higher risk of meningioma progression and recurrence is the expression of the proliferation marker MIB1." (PMID 33287241, 2020). "Increased MIB-1 labeling indices have been associated with an increased risk of recurrence in meningiomas and are sometimes used as an accessory to grading meningiomas." (PMID 17937814, 2007). "MIB-1 labeling index is an established marker for proliferative activity in meningiomas and has been found to be associated with the presence of preoperative brain edema in meningioma patients." (PMID 38715788, 2024). "MIB-1 was associated with meningioma recurrence with a cut-off similar to previous studies." (PMID 36230518, 2022). "Additionally, peritumoral brain edema is significantly associated with a higher MIB-1 labeling index illustrating the proliferative activity of meningiomas." (PMID 34829359, 2021). "This cohort proposes that the role of a high MIB-1 index (>3%) as a key factor associated with meningioma recurrence is limited compared with the literature and only the combination with WHO grade III histology (anaplastic or atypical) may increase the risk of tumor recurrence." (PMID 39790708, 2025). "Moreover, a recent retrospective series evaluating 384 patients who underwent surgery for supratentorial meningiomas revealed that increased MIB-1 labeling indices are significantly associated with Engel class outcomes displaying the postoperative seizure burden." (PMID 36091152, 2022). "The MIB1 labeling index was weak in the MAM component (less than 1% in all cases) whereas it varied from 1% to 8% in the meningioma component." (PMID 38565263, 2024). "The Ki-67/MIB-1 labelling index was a biomarker of meningioma associated with higher WHO grade and indicated the risk for recurrence of meningioma." (PMID 38758750, 2024). "With regard to MIB‐1 LIs, the log‐ratio values of class numbers 8, 9, and 10 were higher in meningiomas with higher MIB‐1 groups (p < .05)." (PMID 37644780, 2023).
meningioma (continued). "With regard to MIB‐1 LI, the ratios of class numbers 8, 9, and 10 tended to be higher in meningiomas with higher MIB‐1 LIs." (PMID 37644780, 2023). "When further exploring the distribution of S100-strong meningiomas, significant differences among many clinical factors were observed, including patient age and the expression of the proliferation marker MIB1." (PMID 35838837, 2023). "Increased MIB-1 labeling indices in meningioma have been demonstrated to be strongly correlated with COX-2 expression." (PMID 36077817, 2022). "In a previous institutional series, we identified that the MIB-1 labeling indices in spinal meningiomas are significantly lower compared to the cranial meningiomas." (PMID 36091152, 2022). "MIB-1 index is an established immunohistochemical marker reflecting the proliferative potential in meningiomas." (PMID 36077817, 2022). "An increased MIB-1 labeling index is inversely correlated with time to tumor progression in SM and has a positive correlation with the grading of meningiomas." (PMID 36091152, 2022). "A higher rate of immunopositivity was seen in higher grade meningiomas, and a correlation with increased micro-vessel density and MIB-1 expression was demonstrated, suggesting a possible link between more aggressive meningiomas and higher SSTR2A expression." (PMID 34601710, 2022). "Increased MIB-1 indices are inversely associated with the time to tumor progression and correlate with the WHO grade of meningiomas." (PMID 35205781, 2022). "In the present series we observed a trend that PC meningiomas exhibiting an increased MIB-1 index are overlapped by the simultaneous presence of dense CD68+ macrophage infiltrates." (PMID 35877258, 2022). "The first case is a right-sided frontal convexity meningioma with both an increased MIB-1 index (10%) and diffuse infiltrates of CD68+ macrophages." (PMID 35205781, 2022). "MIB-1 labeling indices at the initial diagnosis are significantly and inversely correlated with the time to recurrence of cranial meningiomas (p = 0.045, r = −0.507)." (PMID 35453901, 2022). "MIB-1 index is an important predictor of meningioma progression and was found to be correlated with COX-2 expression." (PMID 36077817, 2022). "MIB-1 labeling index is known to correlate with the growth rate of primary untreated meningiomas as well as the regrowth of surgically treated meningiomas." (PMID 36091152, 2022). "MIB-1 labeling indices were further investigated with regard to the postoperative ambulatory mobility in spinal meningioma patients at 3 months after surgery." (PMID 35205781, 2022). "Several previous studies investigated clinical prognostic factors for grade 2 meningiomas, which included age, sex, extent of resection, tumor invasiveness (i.e., brain or bone invasion), and higher MIB-1 labeling index." (PMID 35996160, 2022). "The MIB-1 labeling indices of the recurrent meningiomas are also significantly and inversely correlated with the time to recurrence of the cranial meningiomas (p = 0.003, r = −0.698)." (PMID 35453901, 2022). "Unfortunately, data on biological markers, such as the Ki-67 index or MIB-1, were unavailable for a lot of patients and this impedes us further in our analysis of the molecular profile of our atypical meningiomas." (PMID 33919475, 2021). "The importance of genetics and biomarkers such as MIB-1 and Ki-67 is very well established in the management of meningiomas, at first surgery as well as whenever recurrence occurs." (PMID 32641701, 2020). "MIB‐1 staining is quite helpful to recognize the proliferative ability of meningioma cells, but surgical strategy cannot be modified based on this information because it is unavailable during surgery." (PMID 30993844, 2019). "MIB‐1 LI has been well established for assessing the proliferative ability of meningioma cells and predicting recurrence." (PMID 30993844, 2019).
meningioma (continued). "Some studies have shown that levels of CDKN1A (p21) immunoexpression correlated with MIB-1 immunoexpression in meningioma and increased with increasing tumor grade." (PMID 29662628, 2018). "We present our institution’s (Louisiana State University in Shreveport, Louisiana) data for the immunoreactivity to MIB-1 or Ki-67 labeling index (LI) for the recurrence of meningioma." (PMID 29312841, 2017). "Using immunohistochemistry, the expression of MIB-1 and survivin were determined as labeling indices (LIs) in tissue micro arrays from 160 human meningiomas." (PMID 28953948, 2017). "Both the expressions of MIB-1 and survivin were higher in grade II meningiomas compared with grade I (P ≤ 0.022)." (PMID 28953948, 2017). "Histological features of the included tumors were studied focusing on subtypes and MIB-1 immunoreactivity and compared with MIB-1 immunoreactivity in an age and gender-matched control group of patients with supratentorial meningioma." (PMID 27070421, 2016). "A larger multivariate study on a larger population is needed to confirm the prognostic value of MIB-1 antigen, PR, cathepsin B and cathepsin L on meningioma cells." (PMID 22933900, 2010). "In the present study, we focused on expression of the MIB-1 antigen, PR, cathepsin B and cathepsin L on meningioma cells." (PMID 22933900, 2010). "Comparing different meningioma grades, we showed that higher meningioma grades express more MIB-1 antigen, less PR and more cathepsins B and L. Differences between BM and MM were statistically important in all four parameters." (PMID 22933900, 2010). "While the MIB-1 labeling indices of the high proliferative Grade 2 meningiomas (median = 8.1; Range = 7.5–8.0) were higher than the low-proliferative Grade 2 meningiomas (median = 5.1; Range = 3.7–7.0), larger sample numbers are required to confirm this trend." (PMID 17937814, 2007). "High-proliferative atypical meningiomas had an elevated median MIB-1 labeling index and a greater frequency of copy number aberrations (CNAs) compared to low-proliferative atypical meningiomas." (PMID 17937814, 2007). "MIB-1 labeling data, cytogenetic data and the clinical data are all consistent with the classification into low-proliferative and high-proliferative meningiomas." (PMID 17937814, 2007). "In meningiomas, MIB-1 correlates with recurrence, with a proposed 4.1% cutoff." (PMID 42274815, 2026). "Furthermore, WHO grade 2/3 meningiomas (p = 0.012), perioperative seizures (p = 0.024), subtype (p = 0.016), tumor laterality (p = 0.04), higher MIB-1 index (p < 0.001) and tumor volume (p = 0.01) were also significantly associated with PTBE." (PMID 41632362, 2026). "The use of MIB‐1 LI as a prognostic indicator in meningioma has been the subject of many studies." (PMID 37644780, 2023). "MIB-1 index is an important predictor of meningioma progression." (PMID 36091152, 2022). "In both reoperated recurrent meningioma patients, the secondary MIB-1 labeling indices were higher." (PMID 35453901, 2022). "Consequently, the data emphasize the importance of stringently following up with meningioma patients with an increased MIB-1 labeling index even in case of a gross total resection." (PMID 36077817, 2022). "Adjuvant radiotherapy might be an option in those meningioma patients with an elevated MIB-1 labeling index or in those meningiomas that were subtotally or partially resected." (PMID 35453901, 2022). "Hence, sufficient predictors of MIB-1 labeling indices in spinal meningiomas have to be investigated separately from cranial meningiomas." (PMID 36091152, 2022). "Furthermore, numerous investigations and a recent meta-analysis have proven that the Ki-67/MIB-1 labeling index is an independent predictor of tumor progression in meningiomas." (PMID 35453901, 2022).
meningioma (continued). "This inverse association between plasma fibrinogens and an increased or increasing MIB-1 index in cranial meningiomas might be explained by the potential autocrine secretion of interleukin-6 (IL-6) by human meningioma cells." (PMID 35453901, 2022). "Moreover, the correlation of CT-imaging signs such as calcification with the immunohistochemical variable MIB-1 labeling index was also investigated in a retrospective series investigating 342 consecutive meningioma patients." (PMID 36091152, 2022). "Furthermore, MIB-1 index was investigated as a biological factor known to be correlated with tumor recurrence in meningioma and tumor grading." (PMID 34172069, 2021). "Moreover, numerous studies and a recent meta-analysis have shown that the Ki-67/MIB-1 labeling index is an independent predictor of progression-free survival (PFS) in meningiomas." (PMID 34298854, 2021). "MIB-1 expression in tumor lesions directly correlates with tumors’ proliferation rates and thus may aid in predicting meningioma recurrence." (PMID 32642722, 2020). "One of these cranial meningiomas (P6_C1) was noted to have high MIB1 staining (10–15%) and was considered worrisome for more aggressive clinical behavior but was graded as WHO grade 1 based on histopathology and the absence of > 4 mitotic figures per 10 high-power fields (hpf)." (PMID 32724039, 2020). "Ki67 (MIB-1) is a valuable guide to malignancy in meningioma." (PMID 28860959, 2017). "MIB-1 is the currently used prognostic biomarker in clinical practice in human meningiomas." (PMID 28953948, 2017). "MIB-1 antigen expression was higher in the recurrent meningioma group (p=0.001)." (PMID 22933900, 2010). "Therefore, we did not regard the meningioangiomatosis component of the lesion as the brain invasion by atypical or clear cell meningioma because high level of MIB-1 index is known to be detected in meningiomas of brain invasion." (PMID 20565869, 2010). "Furthermore, some patients with high‐grade meningiomas could have lower MIB‐1 LIs, whereas some patients with low‐grade meningiomas could have higher MIB‐1 LIs." (PMID 37644780, 2023). "In general, DTcIs could also distinguish the lesions of meningiomas with higher MIB‐1 LIs." (PMID 37644780, 2023). "Moreover, adjuvant radiation treatment might be a potential therapy strategy in those patients with an increased MIB-1 labeling index or after partial resection of meningiomas." (PMID 35205781, 2022). "Furthermore, skull-base meningiomas were found to have a significantly lower MIB-1 labeling index and the feasibility of a gross total resection might be more challenging compared to convexity or falcine meningiomas." (PMID 35453901, 2022). "Hence, MIB-1 labeling indices might be a potential marker for location-specific symptoms of meningiomas." (PMID 36091152, 2022). "Moreover, a recent retrospective investigation of 239 WHO grade I meningiomas revealed a recurrence rate of 18.8% in patients with a GTR and a MIB-1 labeling index >4.5%, which resulted in a similar risk of recurrence as patients who underwent a subtotal resection." (PMID 34298854, 2021). "We identified that meningiomas with an increased MIB-1 labeling index and those who did not receive perioperative Dex therapy were associated with an increased likelihood of persistent postoperative T2/FLAIR hyperintensity zones." (PMID 38715788, 2024). "Furthermore, loss of the NF2 suppressor gene at chromosome 22 has been demonstrated in a higher percentage (50–60%) of meningiomas, and supratentorial meningiomas with NF2 alterations had higher MIB-1 indices and a shorter time to tumor progression." (PMID 37370707, 2023).